MDM2 (MDM2 proto-oncogene)
Diseases named in the same sentence as MDM2 in open-access papers (continued):
Sharing a sentence is not in itself a finding about the gene and the disease.
cancer (continued). "In this review, we discuss the precise role of deregulated MDM2 levels in modulating cellular functions to promote cancer growth." (PMID 37314603, 2023). "Small-molecule MDM2 inhibitors have been detected in clinical trials for improving the efficacy of cancer treatment." (PMID 37215134, 2023). "Etoposide, an inhibitor of MDM2, is clinically used for the treatment of several cancers by inhibiting topoisomerase II, an enzyme responsible for DNA strand ligation during cell division." (PMID 36837574, 2023). "Alterations in the expression levels of MDM2 occur in multiple types of cancers resulting in uncontrolled proliferation." (PMID 37314603, 2023). "Through DIANA analysis, miR-214-3p appears to influence another gene, the MDM2, which is involved in cancer pathways." (PMID 37374977, 2023). "Many therapeutics, which are inhibitors of Mdm2 or Mdm4, have entered clinical trials but have yet to be proven to be safe and effective in cancer treatment, such as milademetan, RG7112, RG7388, CGM097, HDM201, and ALRN-6924." (PMID 36362074, 2022). "We provided biochemical and cellular evidence suggesting Hinokiflavone is a promising small molecule with anti-cancer potential through inhibition and downregulation of MDM2 in cancer cells." (PMID 35625571, 2022). "As well as with oncogene expression, the decrease in MYC expression at 100 μg/mL, in TYMS at 500 μg/mL, and in MDM2 at 250 μg/mL was significantly lower than MTX as a commercial cancer drug." (PMID 35529172, 2022).
cancer (continued). "A clear correlation of MDM2 overexpression with poor clinical prognosis and poor response to cancer therapies has been demonstrated over the past decades." (PMID 35408841, 2022). "Upregulation of MDM2 has been reported in a variety of human cancers, which critically correlated with cancer progression and chemotherapeutic resistance." (PMID 35955808, 2022). "To test if these transcriptional effects are observed in normal cells as well as cancer models, we treated hTERT-immortalized melanocyte cells with the MDM2 inhibitor Nutlin-3a." (PMID 35159215, 2022). "Overexpression of MDM2 is often seen in various human cancers and correlated with high-grade, late-stage tumor." (PMID 36439106, 2022). "Although the number of PROTACs recruiting MDM2 is still reduced, they have enormous potential in certain types of cancer, with a focus on those in which both the POI and E3 ligase are overexpressed." (PMID 36232374, 2022).
cancer (continued). "Combinatory treatment with Sorafenib, mostly resulted with downregulation of hub proteins JUN, INSIG1, MDM2 and SOX9 associated with cancer cells." (PMID 35331184, 2022). "Hinokiflavone was shown to downregulate MDM2 and its homolog protein MDMX and inhibit the tumorigenic activity of MDM2 in cancer cells." (PMID 35625571, 2022). "Another MDM2 inhibitor DS-3032b (Rain-32/Milademetan) has entered clinical trials for MDM2-amplified cancers, including Merkle cell cancers, among others." (PMID 35454137, 2022). "Some indole derivatives, which are reported as anti-cancer agents targeting MDM2 and MDMX (1b, RO-2443), have been modified to improve the activities and explore new mechanisms." (PMID 35744849, 2022).
cancer (continued). "Nevertheless, while EIF4A3 is an essential protein these combined effects, including mis-splicing of MDM2, should be further explored in cancer treatment." (PMID 35444234, 2022). "Summary table of all MDM2-based PROTACs created to date for the treatment of several types of cancer." (PMID 36232374, 2022). "In order to promote the apoptosis of cancer cells, Yu Rao’s research group created an MDM2-based PROTAC that targets PARP1 to obtain a new therapeutic weapon in BC." (PMID 36232374, 2022). "Although several preclinical studies have shown impressive results, the limited clinical trials of MDM2 inhibitors in other cancers have been disappointing." (PMID 35965531, 2022). "MDM4 (also known as MDMX) is the only MDM2 homolog that is expressed at levels higher than MDM2 due to its increased expression and protein stability in most cancer types." (PMID 36431769, 2022). "MDM2 inhibitors have demonstrated promising antitumor activity across a range of preclinical cancer models." (PMID 36362209, 2022). "Nevertheless, this finding offers insight into the future design of drug combinations of NMD and MDM2 inhibitors in cancer treatment." (PMID 36180435, 2022).
cancer (continued). "Another well-known E3 is MDM2 which is widely observed in many cancers including breast cancer and lung cancer." (PMID 35064108, 2022). "We have listed several representative PROTACs based on CRBN, VHL, MDM2, or cIAP1 E3 ligases, and PROTACs that are undergoing anti-cancer clinical trials." (PMID 36557960, 2022). "Increasing knowledge in this field will facilitate repurposing and tailoring existing therapies towards cancers that can benefit from MDM2-targeting interventions." (PMID 35155432, 2022). "MDM2 is highly expressed in most tissues as well as in several cancers, likely due to its role as a proto-oncogene." (PMID 36500212, 2022). "MDM2 inhibitors have been reported to combine with other agents for cancer therapies, such as CDK4/6 inhibitors and 5-azacitidine." (PMID 36180435, 2022). "The Mdm2-positive cancer cells were located mainly around the cancer island, especially in the poorly differentiated samples (Figures-4a and b)." (PMID 35369583, 2022).